AMBRA1 (autophagy and beclin 1 regulator 1)
Diseases named in the same sentence as AMBRA1 in open-access papers (continued):
Sharing a sentence is not in itself a finding about the gene and the disease.
melanoma (continued). "Although metastases were not macroscopically visible, histological analyses revealed that lungs from sBPA−/− mice exhibited increased homing and larger nodules than sBPA+/+ mice, suggesting that Ambra1 depletion promotes melanoma metastasis." (PMID 33953176, 2021). "In support to this, we have also observed that AMBRA1-low-expressing human melanoma cell lines and tumors (patient data from the TCGA database and LMC cohort) exhibit upregulation of FAK1 signaling, ECM remodeling, EMT and invasiveness genes." (PMID 33953176, 2021). "Overall, these results indicate that AMBRA1 regulates FAK1 signaling in melanoma cells independently from its PP2A- and autophagy-related functions." (PMID 33953176, 2021). "Overall, this evidence indicates that low expression of AMBRA1 correlates with an invasive phenotype and increased sensitivity to FAKi in human melanoma cells." (PMID 33953176, 2021). "However, strikingly, when epidermal loricrin expression was combined with epidermal AMBRA1 expression, the results revealed that decreased peritumoral expression of both markers was associated with 100% sensitivity and specificity for identifying truly high‐risk melanomas in this subcohort." (PMID 31056744, 2020). "Peritumoral AMBRA1 expression was evaluated in a retrospective discovery cohort of 76 AJCC stage I melanomas." (PMID 31056744, 2020). "We have recently identified the expression levels of Sequestosome1/SQSTM1 (p62) and activating molecule in Beclin 1-regulated autophagy protein 1 (AMBRA1) as novel independent prognostic biomarkers for early stage melanomas." (PMID 27882308, 2016). "In addition to a potential lineage association, oncogenic KRAS signaling is the best predictor for a tumor suppressive role of AMBRA1 in LUAD, and oncogenic BRAF signaling correlates with AMBRA1 tumor suppressive activity in melanoma in DepMap." (PMID 39617889, 2024). "A growing number of studies have reported that AMBRA1 functions as a tumor suppressor in melanoma." (PMID 39720719, 2024). "In fact, all genetic mouse models describing tumor suppressive activity of AMBRA1 so far have been generated on a mutated KRAS/BRAF/MAPK signaling background, and mutations of the KRAS/BRAF/MAPK pathway are common in DLBCL, LUAD, and melanoma." (PMID 39617889, 2024). "Indeed, while knockout of AMBRA1 did not affect the vast majority of cell lines, individual primary diseases showed a unique response pattern, and knockout effects in melanoma and rhabdoid cancer cell lines suggested a tumor suppressive role for AMBRA1." (PMID 39617889, 2024). "Furthermore, that study demonstrated that Ambra1 deletion promotes melanoma invasiveness and metastasis by increasing cell motility/invasion." (PMID 37225761, 2023). "Interestingly, AMBRA1 plays an oncogenic role in hepatocellular carcinoma, metastatic breast cancer, and medulloblastoma, whereas AMBRA1 seems to be a tumor suppressor in colorectal cancer cell, melanoma, and squamous cell carcinoma." (PMID 36237336, 2022). "Notably, many types of cancer, including malignant melanoma, where AMBRA1 has been shown to play an anti-tumorigenic role, show genetic alterations in AMBRA1." (PMID 36243772, 2022). "The prediction of pathogenic mutations of AMBRA1 and their in vitro validation have been carried out in melanoma, the most aggressive and lethal form of skin cancer, in which AMBRA1 not only bears an anti-tumorigenic function, but also displays high mutation rate." (PMID 36243772, 2022). "Interestingly, all these phenomena were not related to the pro-autophagy functions of AMBRA, thus suggesting the existence of compensatory events and a new therapeutic strategy proposing FAK1 inhibition for AMBRA1 low-expressing melanoma." (PMID 34830777, 2021). "This evidence supports the hypothesis that Ambra1 deletion accelerates melanoma progression and promotes the invasive state of melanoma." (PMID 33953176, 2021).
melanoma (continued). "Although this evidence should be validated in vivo through FAK1 genetic ablation in order to circumvent possible off-target effects of pharmacological inhibition, concomitant silencing of FAK1 and AMBRA1 in vitro confirmed the reduced propensity of melanoma cells to migrate and invade." (PMID 33953176, 2021). "Also, we demonstrate that Ambra1 deletion promotes melanoma aggressiveness and metastasis by increasing cell motility/invasion and activating an EMT-like process." (PMID 33953176, 2021). "Notably, we observed an Ambra1 dose-dependent impact on melanoma development, as showed by tumor growth and median survival of Ambra1 heterozygous (BPA+/−) mice." (PMID 33953176, 2021). "Moreover, we also observed that non-lethal doses of FAKi were effective and distinctly altered the invasive/migratory capacity of selected AMBRA1-low-expressing human melanoma cell lines." (PMID 33953176, 2021). "AMBRA1 was identified as an independently prognostic biomarker for early-stage melanomas." (PMID 34194501, 2021). "However, we were not able to correlate either the pro-invasive state of BPA−/− melanoma or the hyperactivation of FAK1 signaling to the AMBRA1 pro-autophagy functions." (PMID 33953176, 2021). "We have identified two protein markers, autophagy and beclin 1 regulator 1 (AMBRA1) and loricrin, in the epidermis overlying primary melanomas, whose expression is lost in high‐risk AJCC stage I melanomas, but which are retained over genuinely low‐risk tumours." (PMID 31056744, 2020). "Moreover, we show that Ambra1 deficiency in melanoma impacts extracellular matrix remodeling and induces hyperactivation of the focal adhesion kinase 1 (FAK1) signaling, whose inhibition is able to reduce cell invasion and melanoma growth." (PMID 33953176, 2021). "Indeed, AMBRA1 expression levels in the tumor tissue have not yet been associated with any stage/feature of melanoma." (PMID 33953176, 2021). "Immunohistochemistry was used to analyse AMBRA1 and TGF‐β2 in a cohort of 109 AJCC all‐stage melanomas, and TGF‐β2 and claudin‐1 in a cohort of 30 or 42 AJCC stage I melanomas, respectively, with known AMBRA1 and loricrin (AMLo) expression." (PMID 34773645, 2022). "Overall, our findings identify a function for AMBRA1 as tumor suppressor in melanoma, proposing FAK1 inhibition as a therapeutic strategy for AMBRA1 low-expressing melanoma." (PMID 33953176, 2021). "Taken together, our discoveries pinpoint AMBRA1 as tumor suppressor in melanoma, and suggest the potential use of FAK1 inhibitors in current melanoma therapy for AMBRA1-low tumors." (PMID 33953176, 2021). "Also, AMBRA1 expression negatively correlated with the expression of the mesenchymal genes CDH2, FN1 and VIM, whereas a positive correlation was evident for the epithelial marker CDH1, hence suggesting that an active EMT-like process is associated with low AMBRA1 expression in human melanoma cells." (PMID 33953176, 2021). "Herein we describe the discovery and validation of the combined expression of two protein biomarkers, AMBRA1 and loricrin, in the epidermis overlying primary AJCC stage I melanomas as a highly sensitive and specific prognostic biomarker." (PMID 31056744, 2020). "The combination of AMBRA1 and loricrin expression represents an independent prognostic biomarker in non-ulcerated AJCC Stage I and II melanoma, which can stratify patients at a low risk of disease recurrence." (PMID 39201498, 2024). "In line with that, genetic alterations of both AMBRA1 and BRAF are prevalent in melanoma, while no AMBRA1 alterations have been identified in ATRT so far." (PMID 39617889, 2024). "Although this can argue for AMBRA1 being prognostic of melanoma outcome, a direct role of AMBRA1 in this disease has not yet been investigated." (PMID 33953176, 2021).
melanoma (continued). "Three-week-old Tyr::CreERT2/+;BrafV600E/+;Pten−/−;Ambra1+/+ (BPA+/+), Tyr::CreERT2/+;BrafV600E/+;Pten−/−;Ambra1+/− (BPA+/−) and Tyr::CreERT2/+;BrafV600E/+;Pten−/−;Ambra1−/− (BPA−/−) mice were locally treated with 4-OHT on the skin of the lower back to initiate melanoma." (PMID 33953176, 2021). "In particular, we show that the absence of Ambra1 promotes the formation of melanocytic nevi and accelerates melanoma growth, eventually enhancing metastatic potential." (PMID 33953176, 2021). "Among them, we found several autophagy-related genes such as AMBRA1, ATG5, ATG12, ATG13 and ATG4B, which could be potentially downregulated in BRAFi-resistant melanoma cells." (PMID 30254376, 2019). "Unlike p62, however, the expression of AMBRA1 in primary melanomas is variable and as such its value as a tumoral biomarker remains undefined." (PMID 27882308, 2016). "However, although these observations provide evidence to support a tumour‐suppressive role for AMBRA1 in melanoma progression, they do not reflect the complex relationship between a heterogeneous melanoma and its microenvironment in human skin." (PMID 34773645, 2022). "Finally, to evaluate whether the AMBRA1 pro-autophagic function participates to the hyperactivation of FAK1, we silenced the key autophagy gene ATG7 (siATG7) in melanoma cells." (PMID 33953176, 2021).
breast carcinoma (9 papers, 2015 to 2025). "It was found that AMBRA1 can negatively regulate apoptosis and growth in prostate cancer and breast cancer cells and is related to AMBRA1-mediated autophagy promotion." (PMID 38393538, 2025). "Ambra1 (autophagy/Beclin 1 regulator 1) regulated the Akt/FoxO1/Bim pathway and conferred to cell apoptosis and chemosensitivity in breast cancer cells." (PMID 38773471, 2024). "The same group also found that AMBRA1 expression level was negatively correlated with the sensitivity of breast cancer cells to epirubicin previously." (PMID 36237336, 2022). "AMBRA1 depletion potentiated the metastatic potential of breast cancer cells toward the bones and the lungs in vivo, indicating that the CUL4/AMBRA1-mediated SMAD4 ubiquitylation should be therapeutically investigated in TGF-β-dependent metastatic cancers." (PMID 35136173, 2022). "A study from Strappazzon and colleagues found that GSK-3β phosphorylates MCL-1 to release AMBRA1, while HUWE1 promotes MCL-1 degradation in Hela cells and MCF7 breast cancer cells, highlighting the need for further studies to elucidate molecular mechanisms of AMBRA1 and mito-BCL-2 in mitophagy." (PMID 36237336, 2022). "Interestingly we evidenced the appearance of an authophagic phenotype by Bg treatment as revealed by fluorescence microscopy of LC3-GFP in breast cancer cells together with an increase of different key hallmarks of the autophagic process such as Beclin 1, PI3K III, UVRAG and Ambra1." (PMID 26148846, 2015).
prostate carcinoma (9 papers, 2015 to 2025). A carcinoma that arises from epithelial cells of the prostate gland. "It has also been shown that AMBRA1 prevents apoptosis in prostate cancer cells and enhances their colony formation, resulting in resistance to cisplatin." (PMID 36361635, 2022). "By increasing autophagy, AMBRA1 prevents apoptosis in prostate cancer cells and enhances their colony formation, leading to CP resistance." (PMID 35317831, 2022). "AMBRA1 undergoes overexpression and protects prostate cancer cells against CP-mediated apoptosis, and CASP3 (caspase 3)-mediated PARP (poly(ADP-ribose) polymerase) cleavage." (PMID 35317831, 2022). "Falasca compared 26 prostate adenocarcinoma and 12 normal specimens by immunohistochemistry and observed that AMBRA1 was highly expressed in prostate cancer." (PMID 33604190, 2021). "Our results confirmed such regardlessness of p62 in the Ambra1-induced autophagy and desensitization to cisplatin in human prostate cancer cells." (PMID 29101240, 2019). "This scoring system indicates that levels of AMBRA1 were greater (score 4–5) in tumors with a higher prostate cancer grading system, again suggesting a positive correlation between AMBRA1 positivity and PCa lesions." (PMID 26423274, 2015). "Furthermore, cisplatin-induced autophagy was upregulated by Ambra1 overexpression or downregulated by Ambra1 knockdown in prostate cancer cells." (PMID 37225761, 2023). "Finally, AMBRA-1 is implied in autophagy as well as cell growth, cell death, embryonic development and carcinogenesis; moreover, in pancreatic ductal adenocarcinoma, cholangiocarcinoma and prostate carcinoma, its poor prognostic value has been inferred." (PMID 30893939, 2019). "In the present study we found that: (i) at variance with benign lesion, prostate cancer cells underwent SQSTM1 accumulation, i.e., clearly displayed a defective autophagic process but, also, (ii) prostate cancer accumulated AMBRA1 and (iii) this increase positively correlated with the Gleason score." (PMID 26423274, 2015). "The data reported in this pilot study demonstrated an increased expression of AMBRA1 and SQSTM1, which were also associated with an accumulation of LC3II in prostate cancer but not in benign lesion." (PMID 26423274, 2015). "Accordingly, in the case of AMBRA1 we detected a good correlation with the Gleason score, whereas the SQSTM1 expression levels, previously suggested as not altered in PCa, seem to not correlate with prostate cancer grading system." (PMID 26423274, 2015).
autism (7 papers, 2014 to 2025). Persistent deficits in social interaction and communication and interaction as well as a markedly restricted repertoire of activity and interest as well as repetitive patterns of behavior. "Based on these evidences, we took advantage of Ambra1+/− female mice to shed light on the pathogenic mechanisms specific to female autism." (PMID 36804922, 2023). "Reduced synaptic pruning and increased dendritic spine density have been described as strong correlates of autism; in mice, heterozygotes for loss of AMBRA1 function show female-restricted increases in dendritic spine density." (PMID 31687209, 2019). "We genotyped the AMBRA1 autism-risk SNP in a population of typical humans who were scored for the dimensional expression of autistic and schizotypal traits." (PMID 31687209, 2019). "In the present study, we show an autism-like phenotype in a mouse line, deficient of a central protein, Ambra1, in the autophagy cascade." (PMID 24904333, 2014). "The autophagy-associated gene AMBRA1 represents one of the top genome-wide “hits” in recent GWAS studies of schizophrenia, shows sex-differential expression, and has been linked with autism risk and traits in humans and mice, especially or exclusively among females." (PMID 31687209, 2019). "Loss of function in multiple genes that negatively regulate mTOR, including TSC1, TSC2, PTEN, NF1, and FMR1, has been linked to syndromic autism with increased head size and high rates of seizures; both of these traits are also found in mice heterozygous for AMBRA1 loss of function." (PMID 31687209, 2019). "Human sex differences in autophagy are prominent in the brain and other tissues, with sex-differential effects from genetic variation also found in the autophagy-regulating gene ADNP (Activity-Dependent Neuroprotective Protein), which, like AMBRA1, affects autism and schizophrenia risk and traits." (PMID 31687209, 2019). "The gene AMBRA1 (Activating Molecule in Beclin 1-Regulated Autophagy) codes for a gene product that shows sex-differential expression and has been linked to autism-related and schizophrenia-related phenotypes, exclusively or predominantly among females, in both humans and mice." (PMID 31687209, 2019). "The question of how AMBRA1/Ambra1 reduction may influence synaptic function, thereby causing the autism-pathognomonic neuronal excitation–inhibition dysbalance, still remains unanswered." (PMID 28994820, 2017). "Thus, in two independent human cohorts, a single normal variant in the AMBRA1 gene, rs3802890, is associated with autism-related behaviors predominantly in females." (PMID 28994820, 2017). "The present study has therefore been designed to explore whether any autism-relevant phenotype association with normal AMBRA1 genotypes would emerge in humans, thereby supporting the construct-validity of our Ambra1+/− mouse model." (PMID 28994820, 2017). "This across-species unique female autism generation by a defined genetic trait that appears to cause partial loss-of-function encouraged us to continue searching for further autism-specific readouts in our Ambra1+/− mouse model." (PMID 28994820, 2017). "Heterozygous Ambra1 deficiency induces autism-like behavior in a sexually dimorphic manner." (PMID 28994820, 2017). "To conclude, Ambra1 deficiency can induce an autism-like phenotype." (PMID 24904333, 2014). "AMBRA1, moreover, represents one of the top genome-wide significant genes for risk of schizophrenia in recent GWAS studies; as such, determining the role of this gene, in autism- and schizophrenia-associated psychological and neurological phenotypes, is crucial to evaluating its functions." (PMID 31687209, 2019). "Notably, a behavioral study on heterozygous Ambra1 mice (Ambra1+/−) revealed an autism-like phenotype that was restricted only to females and a recent work proved an association between autism and intronic single nucleotide polymorphisms of the AMBRA1 gene in human female patients." (PMID 29488136, 2018).